C1orf232 (chromosome 1 open reading frame 230)
Gene: Protein-coding gene on chromosome 1 (26,164,101 to 26,168,963, reverse strand). Ensembl gene ENSG00000282872.
Genetic constraint (gnomAD): Loss-of-function variants: 10 observed, 9.47 expected, observed/expected ratio (o/e) 1.06, 90% interval 0.65 to 1.72. That is too few expected variants to judge how well the gene tolerates losing a copy. Missense variants: 88 observed, 89.19 expected, observed/expected ratio (o/e) 0.99, 90% interval 0.83 to 1.18. Synonymous variants: 36 observed, 34.32 expected, observed/expected ratio (o/e) 1.05, 90% interval 0.8 to 1.38.
Homologues: Orthologues: chimpanzee C1H1orf232 (98% identical), macaque C1H1orf232 (95% identical), guinea pig C1orf232 (88% identical), dog C1orf232 (85% identical), mouse Gm30191 (85% identical), pig C1orf232 (83% identical), rat C5h1orf232 (83% identical), zebrafish C16H1orf232 (28% identical).